CCL4 (C-C motif chemokine ligand 4)
Diseases named in the same sentence as CCL4 in open-access papers (continued):
Sharing a sentence is not in itself a finding about the gene and the disease.
Insulin resistance (11 papers, 2019 to 2025). Increased resistance towards insulin, that is, diminished effectiveness of insulin in reducing blood glucose levels. "In a diet-induced DM model, CCL4-knockout mice had improved blood sugar levels in the oral glucose tolerance tests as well as lower homeostasis in the model assessment of insulin resistance." (PMID 36009510, 2022). "In conclusion, systemic and/or direct inhibition of CCL4 protected pancreatic islet cells, improved insulin resistance, and retarded the progression of hyperglycemia in different experimental DM models." (PMID 33968046, 2021). "In support of this argument, TNF-α, IL-6, IL-8, CCL2, CCL4, CCL5, and CCL19 were found to be implicated with metabolic inflammation or insulin resistance in various tissues and organs." (PMID 31718015, 2019). "Furthermore, inhibiting CCL4 with a specific antibody has been found to attenuate systemic inflammation, improve insulin resistance, and reduce circulating insulin levels in both type 2 diabetes animal models and metabolic syndrome animal models." (PMID 37287987, 2023). "In this study, we focused on the effects of CCL4 inhibition on the levels of TNF-α and IL-6, which may be related to the root causes of insulin resistance in type 2 diabetes." (PMID 33968046, 2021). "More importantly, direct blockade of CCL4 could reverse pancreatic islet cell damage and/or systemic insulin resistance to stabilize the blood sugar levels in both the type 1 and type 2 diabetes models and in the metabolic syndrome animal model." (PMID 33968046, 2021). "In summary, direct inhibition of CCL4 protected pancreatic islet cells, improved insulin resistance and retarded the progression of hyperglycemia in different experimental models, suggesting the critical role of CCL4-related inflammation in the progression of DM." (PMID 33968046, 2021). "CCL4 antibody-treated mice had decreased levels of phosphorylated IRS-1 in both skeletal muscle and liver tissues compared to those in the untreated db/db mice, implying the beneficial effects of CCL4 inhibition on improving insulin resistance." (PMID 33968046, 2021). "Therefore, a reduced expression of CCL4 and CCL5 after administration of CR may decrease inflammation and ameliorate insulin resistance." (PMID 34360840, 2021). "In addition, dual CCR2/CCR5 antagonism could ameliorate insulin resistance and inflammation in high-fat diet-fed mice and decrease CCL2/CCL4‐induced migration of macrophage." (PMID 33968046, 2021).
sarcoidosis (11 papers, 2011 to 2026). Sarcoidosis is a multisystemic disorder of unknown cause characterized by the formation of immune granulomas in involved organs. "In sarcoidosis patients, sarcoidosis increases the attraction of CD4+ T cells through the release of CCL4, either alone or together with Th1/Tc1-associated cytokines." (PMID 26587829, 2015). "Two studies have found associations between elevated levels of CCL3 or CCL4 protein/cell pellet mRNA expression from BALF in patients with sarcoidosis." (PMID 21463523, 2011). "Likewise, Capelli and colleagues demonstrated higher BALF CCL3 and CCL4 protein levels from sarcoidosis patients (n = 30) as compared to healthy controls (n = 18)." (PMID 21463523, 2011). "BALF CCL3 and CCL4 protein levels measured by enzyme-linked immunosorbent assay (ELISA) were not significantly elevated in patients with sarcoidosis (n = 72) compared with normal healthy controls (n = 8)." (PMID 21463523, 2011). "Meanwhile, the “hsa04060: cytokine–cytokine receptor interaction’ pathway, including the CCL4, CSF1R, CXCR4, FLT1, and IL7 genes, could be highly associated with immune regulation and is strongly suspected to be involved in the pathogenesis of sarcoidosis." (PMID 35860586, 2022). "In addition, through a rigorous interrogation of candidate mutations in genes using available informatic data resources, we envisaged that the highly ranked hub genes among 30 immune-related candidate genes could also contribute to the pathogenesis of sarcoidosis, including CCL4 and CXCR4." (PMID 35860586, 2022). "Sarcoidosis fibroblasts also produced increased levels of chemoattractants (CCL2, CCL4, CCL5, CXCL9), suggesting a role in both maintaining T cell activation as well as in recruiting monocytes and T cells to the tissue microenvironment." (PMID 35668129, 2022). "When comparing to control subjects, the expression levels of CC chemokines CCL3 (P = 0.043), CCL4 (P = 0.034), CCL5 (P < 0.001), and CCL8 (P = 0.031) and CXC chemokines CXCL9 (P < 0.001), CXCL10 (P = 0.002), and CXCL11 (P = 0.008) were found to be elevated in sarcoidosis patients." (PMID 26696750, 2015). "SPP1hi macrophages coexpressing CCL4 and CCL5 are not a dominant feature in systemic sclerosis or sarcoidosis." (PMID 39989459, 2025).
colorectal cancer (10 papers, 2014 to 2025). A primary or metastatic malignant neoplasm that affects the colon or rectum. "In colorectal cancer, higher β-catenin levels led to an inhibition of CCL4, a proinflammatory chemokine, and subsequently lower recruitment of CD103+ DCs thus impairing CD8+ T cell activation." (PMID 40130164, 2025). "We noticed that the CCL2 and CCL4 areas under the ROC curve (0.634; 0.630, respectively) in the entire group of colorectal cancer were highest from all newly tested parameters, but lower than AUC for CEA and CRP." (PMID 35407400, 2022). "They found that CCL4 levels were obvious upregulated in colorectal carcinomas tissue as compared with controls." (PMID 25401103, 2014). "That is why the aim of our study was an attempt to clarify and to assess the usefulness of selected CC-chemokine measurement (CCL2, CCL4 and CCL15) in patients with colorectal cancer compared to the healthy volunteer group." (PMID 35407400, 2022). "The antibody array chemokine enrichment analysis chart shows that the chemokines CCL3, CCL4, and IL8 were highly expressed in colorectal cancer tissues and metastatic lymph nodes; however, they were downregulated in the normal, adjacent, and adenoma groups." (PMID 35935327, 2022). "Because CCL4 did not achieve the expected results in the subsequent cell verification process, the high expression of IL8 factor in colorectal cancer and a variety of cancers has been confirmed." (PMID 35935327, 2022).
depression (10 papers, 2015 to 2025). "Previous findings in a mouse model of depression show that plasma levels of MIP-1β/CCL4 are elevated by stress and linked to elevated hippocampal mRNA expression of TLR4." (PMID 34226490, 2021). "In a fully adjusted model, depression was significantly associated with higher levels of IFN-γ and IL-1ra; IL-33, CCL-2, CCL-4 and TNF- α remained significant below the Bonferroni threshold." (PMID 39922907, 2025). "Using a multivariate linear model, high serum levels of MIP-1β/CCL4 and Eotaxin/CCL11 remained associated with depression (p < 0.01), while, IL-8/CXCL8, MIP-1β/CCL4, MCP-1/CCL2, and MIP-1α/CCL3 were associated with anxiety (p < 0.05) in the symptomatic groups." (PMID 34863117, 2021). "CCL4 is an initiator of the inflammatory processes, suggesting inflammatory pathways are reduced in activity following sleep restoration and reduction in depression symptoms." (PMID 25983695, 2015). "A role for MIP-1β/CCL4 in depression has been reported in different contexts." (PMID 34226490, 2021). "Greater CCL4 activity is linked to major depressive disorder in both adolescents and adults; however, it is not clear if the activity of this gene or other inflammatory initiating genes change following sleep improvement and mood change." (PMID 25983695, 2015). "Further studies are needed to demonstrate that other chemokines, such as CCL4, CXCl4, CXCL7 and CXCL8, proposed as being altered in depression are also sensitive to CBT interventions." (PMID 31974503, 2020). "Individuals with depression had higher levels of blood CXCL4 and CXCL7 and lower levels of blood CCL4." (PMID 29133955, 2018). "When compared with participants without depression or subsequent cognitive decline, patients with LLD were shown to have elevated concentrations of CCL-2 and CCL-4 and cytokines IL-17a, IL-33, IFN-γ and IL-1ra, as well as IL-33 in most models." (PMID 39922907, 2025). "This meta-analysis indicates that a number of these chemokines (CCL2, CCL3, CCL4, CCL11, CXCL4, CXCL7 and CXCL8) when measured in the blood discriminate between those with and without depression." (PMID 29133955, 2018).
glioma (10 papers, 2015 to 2025). A benign or malignant brain and spinal cord tumor that arises from glial cells (astrocytes, oligodendrocytes, ependymal cells). "For instance, midkine, released by retinal ganglion cells, stimulates CD8+ lymphocytes to secrete the chemokine CCL4, which subsequently activates glioma-associated microglia or macrophages to secrete CCL5." (PMID 40092993, 2025). "Additional validation indicated that serum CCL4 levels were notably higher in patients with central nervous system inflammation than in those with gliomas." (PMID 39364412, 2024). "In the context of gliomas, CCL4 aids in tumor progression by altering the tumor microenvironment, thereby facilitating tumor growth, invasion, and the formation of new blood vessels." (PMID 39364412, 2024). "To confirm our findings, we collected serum again from clinical patients diagnosed with brain inflammation disease and glioma and measured the CCL4 levels present." (PMID 39364412, 2024). "A clinical study analyzing serum samples from 19 glioma patients and 22 patients with central nervous system inflammation diseases revealed that CCL4 levels were notably elevated in the inflammatory group compared with the glioma group (p < 0.001)." (PMID 39364412, 2024). "Our results indicated that the expression of CCL4 in cases of brain inflammation disease was notably higher compared with that in glioma, and this difference was statistically significant (p < 0.001, AUC = 0.8182)." (PMID 39364412, 2024). "Taken together, these results establish Ccl4 as the cytokine responsible for inducing microglia Ccl5 production relevant to glioma growth regulation." (PMID 32358581, 2020). "HBS-101, a novel midkine inhibitor, reduced optic nerve proliferation, normalized RNFL thickness, and decreased the expression of tumor (Neu4, Gpr17) and TME (Ccl2, Ccl3, Ccl4, Ccl5) genes, supporting its continued development as a targeted therapy for pediatric NF1-associated glioma." (PMID 41497446, 2025). "Our findings indicate that serum CCL4 could serve as a potential marker for identifying between intracranial inflammation disease and gliomas." (PMID 39364412, 2024). "We found that CCL4 levels were notably elevated in cases of encephalitis compared with glioma, suggesting that it could serve as a potential biological marker." (PMID 39364412, 2024). "In this manner, Nf1-mutant neurons initiate a paracrine stromal cascade in which midkine induces CD8+ T cells to produce Ccl4, which in turn stimulates TAM expression of Ccl5, a cytokine that increases glioma growth." (PMID 41497446, 2025). "In contrast, levels of IL-4, IFN-α, IFN-γ, IL-6, TNF-α, CCL4, P-cadherin, TRAIL, CCL11, and VEGF were significantly higher in serum than in CSF for both glioma and brain inflammation groups." (PMID 39364412, 2024). "The levels of serum factors IL-4, IFN-α, IFN-γ, IL-6, TNF-α, CCL4, CCL11, and VEGF were found to be significantly higher in gliomas compared with inflammatory diseases of the central nervous system (p < 0.05)." (PMID 39364412, 2024). "Moreover, we demonstrate that NF1-mutant neurons support glioma growth by producing MDK, which activates T cells to produce Ccl4, a cytokine that induces microglia to express a critical glioma growth factor (Ccl5)." (PMID 32358581, 2020).
leprosy (10 papers, 2013 to 2025). Leprosy is a chronic infectious disease affecting primarily the skin and peripheral nervous system. "As we envisage use of MBT strips both as POC tests and as user-friendly rapid tests for overnight stimulated whole blood samples, CCL4 as a biomarker for PB leprosy was included as the sixth biomarker." (PMID 33490914, 2021). "The levels of CCL4 and S100A12 showed a significant result in both the correlation and cross-sectional analysis, indicating an association of these markers with leprosy and/or M. leprae infection among HCs." (PMID 32849645, 2020). "The detection of cellular markers (IP-10 and CCL4) further improved the sensitivity of BT/TT leprosy patients up to 54%." (PMID 30560920, 2018). "CCL4 was also observed recently as a potential biomarker to distinguish leprosy patients and controls of areas endemic, as Brazil." (PMID 23798993, 2013). "In addition, CCL4 showed added diagnostic value in overnight stimulated WBA samples, particularly for patients with PB leprosy and was also associated with M. leprae infection among household contacts." (PMID 33490914, 2021). "Importantly, overnight stimulation with M. leprae antigens, as demonstrated for the patient with PB leprosy, increased CCL4 levels which were undetectable in unstimulated samples/sera." (PMID 33490914, 2021). "Finally, several genes clustered in the 17q11–q21 region, such as chemokines CCL2, CCL3, CCL4, CCL5 and CCL7, were also linked to leprosy." (PMID 23798993, 2013). "They evaluated the levels of anti-PGL-1 IgM antibody as well as IP-10, CCL4 and CRP in blood collected from leprosy patients and observed that combined detection of these biomarkers significantly improved the diagnostic potential, particularly for PB leprosy in all studied regions." (PMID 35416839, 2022). "Moreover, anti-PGL-I IgM levels could not be used to discriminate PB patients or (BCG-vaccinated) HHC from EC, which clearly demonstrates the added value of IP-10, IL-10 and CCL4 in leprosy diagnostics." (PMID 27682181, 2016). "Levels of anti-PGL-I IgM antibody (humoral immunity), IP-10, CCL4 and CRP (cellular immunity) were measured in blood collected from leprosy patients, household contacts and healthy controls from each area." (PMID 30560920, 2018). "Samples from leprosy patients showed down-regulation of CCL2, CCL3, CCL4 (p<0.05), while IL1β and SOD2 were borderline significant (p<0.1), confirming a repression of these genes by M. leprae ex vivo, as was observed in vitro in THP-1." (PMID 23798993, 2013). "Overall, the data show that IP-10 was the most significant cellular marker to identify both LL/BL and BT/TT leprosy patients in low- and high endemic populations, anti-PGL-I IgM and CRP are relevant for diagnosis of LL/BL patients and CCL4 contributes to the detection of BT/TT patients." (PMID 30560920, 2018).
liver disease (9 papers, 2007 to 2024). "In in vivo models, they exhibit high efficacy in treating or preventing liver disease mediated by hepatotoxic xenobiotics such as ethanol, aspirin, and CCL4." (PMID 38794127, 2024). "Herein, we used CCL4 to generate a liver disease model, and the symptoms, liver function, and pathological changes of this model were similar to those of human liver injury." (PMID 36557783, 2022). "The portal hypertension that develops in rodents exposed to CCL4 is the results of extracellular matrix deposition and endothelial dysfunction due to two major mechanisms, i.e. insufficient NO production and enhanced ET-1 generation." (PMID 26539823, 2015). "In portal hypertensive rats related to other models of portal hypertension, like CCL4, CBDL or TAA, the event of bacterial translocation is also produced." (PMID 17999758, 2007). "In studies of liver diseases, CCT showed comparative beneficial effects on CCL4-induced and dengue virus-induced liver damage via induction of antioxidant defense." (PMID 34179049, 2021).
steatosis (9 papers, 2014 to 2025). Increased lipid within the cytoplasm of cells. "We compared the transcription levels of markers of fibrosis, steatosis, inflammation and proliferation in CCl4/ethanol and CCL4/Western diet mouse models." (PMID 37373497, 2023). "According to histologic staining, steatosis, inflammation, fibrosis, and ballooning grade of the CCL4 group were significantly higher than that of the control group." (PMID 39354960, 2022). "In the current study, we present a rat model of NAFLD developed over 8 weeks on a modified FFD with a CCL4 micro dose (0.5 ml CCl4/kg bwt) that captures steatosis, inflammation and fibrosis stages of NAFLD." (PMID 24884574, 2014). "Monoolein, which is one of the most important lipids, has multiple applications in drug delivery, emulsion stabilization, and protein crystallization, while emodin has been associated with weight loss effects due to its lipid-lowering properties and capability to alleviate CCL4-induced steatosis." (PMID 36677059, 2023). "The results show a clear separation between steatosis (in yellow) and non steatosis (in grey) clustering groups, except for CCL4 at day 28 which was grouped with the non-steatotic compounds." (PMID 25470483, 2014). "The plasma level of NT‐3, CCL20, CCL4, CCL3, LIF‐R, OPG, and HGF was higher, and SCF was lower only in the severe steatosis versus no steatosis." (PMID 35128832, 2022).
type 1 diabetes (9 papers, 2016 to 2025). "Furthermore, high maternal levels of circulating inflammatory cytokines (IFN-γ, IL-1β, CCL2, and CCL4) during pregnancy have been associated with increased risk of type 1 diabetes in the offspring." (PMID 35693790, 2022). "Increased serum levels of CCL4 produced by islet cells have also been reported in type 1 diabetes and pre-diabetic condition, as well as in patients with T2D, suggesting the involvement of CCL4 in various stages of this disease." (PMID 29228058, 2017). "Clinically, the circulating CCL4 concentrations may be increased not only in the multiple islet autoantibody-positive group type 1 diabetes patients but also in prediabetic patients." (PMID 27553774, 2016). "In contrast, the concentration of CCL4, which is attributed to a protective effect against the development of type 1 diabetes, was reduced in T1D patients compared to the control group, although without statistical significance." (PMID 38937380, 2024).
Arthritis (8 papers, 2010 to 2026). Inflammation of a joint. "Finally, additional validation using primary RA samples and in vivo arthritis models will be necessary to confirm the relevance of the WISP-3/CCL4 axis and its association with macrophage polarization during disease progression." (PMID 41399379, 2026). "Additionally, patients with arthritis had higher CCL4/MIP-1-β concentrations." (PMID 35456119, 2022). "Using the flow cytometry-based, predesigned Human Chemokine CBA Kit, we detected higher levels of CCL2, CCL3, CCL4, CCL5, CXCL9, and CXCL10 in arthritis than in CTRL plasma." (PMID 28619088, 2017). "While CCL4 has been previously identified in RA ECs this study is the first to quantify its presentation in comparison to control non-RA tissue, where the control tissue is not from another arthritis type." (PMID 28648867, 2017).